NES (nestin)
Diseases named in the same sentence as NES in open-access papers (continued):
Sharing a sentence is not in itself a finding about the gene and the disease.
breast carcinoma (continued). "A significantly low serum Nestin below 39.9 pg/mL and a higher percentage of the T/T homozygous variant allele of HOTAIR rs12826786 C>T were found in Egyptian patients with breast cancer." (PMID 33584136, 2021). "The best cut-off value for serum Nestin to differentiate normal subjects and patients with breast cancer was 39.9 pg/mL." (PMID 33584136, 2021). "It was shown that Nestin knockout in highly metastatic breast cancer cells increased cell stiffness." (PMID 33807338, 2021). "Up to our knowledge, this study is the only study so far evaluated serum Nestin in a cohort of breast cancer patients." (PMID 33584136, 2021). "Serum Nestin ranged between 6.7 and 167.3 pg/mL with a median value of 31.3 in patients with breast cancer compared to a median of 42.3 and a minimum of 25.7 and a maximum of 315.95 pg/mL in normal control women." (PMID 33584136, 2021). "Serum Nestin was significantly lower in patients with breast cancer compared to normal controls (P=0.032)." (PMID 33584136, 2021). "In essence, the current study is the first of its kind to shed light on the pattern of serum Nestin in aspecific cohort of Egyptian patient affected with breast cancer." (PMID 33584136, 2021). "As a consequence, IHC detection of co-expression of nestin and relevant biomarkers provides a novel approach to more precisely predicting the prognosis of breast cancer." (PMID 32467665, 2020). "Nestin-positive breast cancer stem/progenitor cells can differentiate into endothelial cells which would participate in tumor growth and vascularization." (PMID 32467665, 2020). "We first conducted the present meta-analysis to systematically analyze the prognostic impact of nestin expression on breast cancer patients." (PMID 32467665, 2020). "Although the prognostic and clinicopathological impact of nestin expression on breast cancer patients has been assessed in several independent studies, their results remained conflicting." (PMID 32467665, 2020). "Six studies were included in the univariate analysis of the impact of nestin expression on breast cancer-specific survival (BCSS)." (PMID 32467665, 2020). "In summary, this meta-analysis revealed the prognostic value and clinicopathological significance of nestin expression in breast cancer." (PMID 32467665, 2020). "Nestin is also a valuable biomarker for unfavorable clinicopathological features and tumor angiogenesis of breast cancer." (PMID 32467665, 2020). "To address these discrepancies, we performed this meta-analysis to systematically determine the prognostic and clinicopathological impact of nestin on patients with breast cancer." (PMID 32467665, 2020). "Some studies have demonstrated the strong link between increased nestin expression and poor prognosis of breast cancer patients." (PMID 32467665, 2020). "Nestin has been revealed to promote tumorigenesis, progression, metastasis, and angiogenesis of breast cancer." (PMID 32467665, 2020). "We then evaluated the correlation between nestin expression and clinicopathological characteristics of breast cancer patients in this meta-analysis." (PMID 32467665, 2020). "This meta-analysis revealed the prognostic value and clinicopathological significance of nestin expression in breast cancer." (PMID 32467665, 2020). "With slight heterogeneity (P = 0.055, I2 = 53.8%), a random-effects model showed increased nestin expression in patients with breast cancer predicted reduced OS (pooled HR = 1.88, 95% CI [1.31, 2.71], P = 0.0007)." (PMID 32467665, 2020). "We propose the inclusion of FOXA1 and Nestin immunohistochemical evaluation in current immune panels for breast carcinoma to improve prognostication and therapy choice." (PMID 30819139, 2019). "There are currently few reports on the structure, function and clinical importance of Nestin in breast cancer." (PMID 30819139, 2019).
breast carcinoma (continued). "In breast cancer metastases, FOXA1 expression was associated with Nestin-negativity, GATA3-positivity, ER-positivity, HER2-positivity and non-triple-negative status (P < 0.05)." (PMID 30819139, 2019). "In future studies, it would be interesting to investigate FOXA1 and Nestin expression in the primary breast carcinoma corresponding to the 164 metastatic breast carcinomas investigated here." (PMID 30819139, 2019). "In breast cancer, for example, nestin expression in tumors of human patients was shown to be significantly associated with aggressive cancer type with stem-like features." (PMID 31126068, 2019). "No studies have investigated the prognostic value of FOXA1 and Nestin expression in breast cancer metastases." (PMID 30819139, 2019). "Knockdown of Nestin inhibited breast cancer stem cell invasiveness and led to up-regulation of E-cadherin." (PMID 30819139, 2019). "FOXA1 was a significant predictor of favorable outcome in primary breast cancer, while Nestin expression is preferentially found in triple-negative tumors with increased rate of nodal metastases, and reduced survival." (PMID 30819139, 2019). "To date, immunohistochemical analysis of FOXA1 and Nestin expression has only been performed using primary breast carcinomas." (PMID 30819139, 2019). "This is the first report, to our knowledge, showing FOXA1 and Nestin expression in breast cancer metastases." (PMID 30819139, 2019). "In the METABRIC (Molecular Taxonomy of Breast Cancer International Consortium) cohort, patients with high Nestin signature score had a reduced breast cancer specific survival (p = 0.01)." (PMID 28439082, 2017). "Here, Nestin expression in breast cancer has been mapped and validated in multiple cohorts from different populations." (PMID 28439082, 2017). "Nestin protein expression in breast cancer cells was found by immunohistochemistry in 9%, 13%, 28% and 24% of the cases in Series I-IV, respectively." (PMID 28439082, 2017). "Immunohistochemical staining of Nestin was done in independent breast cancer hospital cohorts (Series I-V, total 1257 cases)." (PMID 28439082, 2017). "We are interested in further investigating how Nestin inhibits the growth and metastasis of breast cancers in vivo." (PMID 25056574, 2014). "Among breast cancer subtypes, nestin is highly expressed in the basal subtype (ERα−/PR−/Her2−), but not in the Her2 subtype (ERα−/PR−/Her2+) or luminal epithelial subtype (ERα+/PR+)." (PMID 22580387, 2012). "Furthermore, the rate of nestin expression is one of the important criteria for prognosis in breast cancer." (PMID 35453578, 2022). "In conclusion, our results demonstrated that LncRNA ENST869 could affect the function of Nestin in breast cancer cells treated with Chidamide." (PMID 35444938, 2022). "Nestin, an intermediate filament, is often present in substantial quantities in basal breast cancer and may be a marker for highly aggressive disease." (PMID 35280770, 2022). "Nestin blockade has been shown to inhibit the proliferation of colorectal cancer cell lines, migration, invasion and stemness of lung adenocarcinoma lines and a reduction in the 5-year survival rate has been verified in nestin-positive breast cancer patients." (PMID 33805026, 2021). "Furthermore, a recent study found a positive correlation between Nestin mRNA and Nestin protein expression in germline BRCA1 related breast cancer, a basal-like phenotype, with reduced survival, and stem ness characteristics." (PMID 33584136, 2021). "They observed Nestin positivity in only 9-28% of studied hospital breast cancer patients." (PMID 33584136, 2021). "Nestin is an independent predictor of worse prognosis in breast cancer." (PMID 34291358, 2021). "We evaluated serum Nestin and the HOTAIR rs12826786 C>T polymorphism in healthy Egyptian women and those with breast cancer as a possible screening tool to identify patients with breast cancer." (PMID 33584136, 2021).
breast carcinoma (continued). "Pooled results revealed that increased nestin expression in patients with breast cancer predicted worse BCSS in both subgroups (Direct data group: pooled HR = 2.02, 95% CI [1.68, 2.43], P = 0.01, I2 = 0%; Calculated data group: pooled HR = 2.48, 95% CI [1.75, 3.52], P = 0.01, I2 = 0%)." (PMID 32467665, 2020). "Therefore, it is imperative to elucidate the clinical implication of nestin in breast cancer patients." (PMID 32467665, 2020). "Besides, nestin is also a valuable biomarker for unfavorable clinicopathological features and tumor angiogenesis of breast cancer." (PMID 32467665, 2020). "Enhanced expression of nestin is a promising indicator for the malignancy of breast cancer." (PMID 32467665, 2020). "Therefore, more studies to investigate the relationship between nestin expression and survival outcomes of breast cancer patients are warranted." (PMID 32467665, 2020). "In this present study, FOXA1 and Nestin expression were examined using immunohistochemistry for 164 breast cancer metastases, followed by Cox regression analysis to assess their prognostic significance in breast cancer." (PMID 30819139, 2019). "Similarly, CD44high/CD24low breast cancer stem cells isolated from human tissues transfected with nestin siRNA showed reduced sphere formation, cell cycle arrest at G2/M, and increased apoptosis." (PMID 31126068, 2019). "Here, the main objective was to evaluate Nestin expression in larger breast cancer series and to explore whether this marker can predict BRCA1 associated cancers." (PMID 28439082, 2017). "What is more, NC could inhibit cellular CSCs-like self-renewal capacity of breast cancer by inhibiting the expression of pluripotency maintaining transcription factors (Nanog, Nestin and Oct-4) and CSCs markers (CD44) as well as the components of Hh pathway." (PMID 27313840, 2016). "Our findings therefore suggest that Nestin may be a potential therapeutic target for the prevention of breast cancer metastasis." (PMID 25056574, 2014). "Breast CSC express Nestin and are crucial for the development and progression of breast cancer." (PMID 25056574, 2014). "We investigated Nestin expression in triple-negative breast cancer and examined how the modulation of Nestin expression affects cell cycle progression, survival, invasion and regulatory signaling in breast cancer stem cells (CSC) in vitro." (PMID 25056574, 2014). "“Among the breast cancer subtypes, nestin is highly expressed in basal breast cancer subtype”." (PMID 23216862, 2012). "Nestin, an intermediate filament protein expressed preferentially in proliferating endothelial cells, has been proposed as a complementary marker of active angiogenesis and has been investigated in several solid tumor types, including pancreatic, colorectal, and breast carcinomas." (PMID 42122290, 2026). "Additionally, inhibiting nestin in breast cancer stem cells could increases GSK-3β and E-cadherin, decreases β-catenin, N-cadherin and vimentin to reduce proliferation and invasion of CSCs." (PMID 40799240, 2025). "Nestin induces the expression of N-cadherin, thereby promoting EMT in breast cancer and pancreatic ductal carcinoma." (PMID 40799240, 2025). "In breast cancer, dormant cells are also in close proximity to endomucin+ perivascular niches and specifically regulated by NG2+Nestin+ mesenchymal stromal cells (MSCs)." (PMID 41091336, 2025). "Breast cancer disseminated tumor cells (BC DTCs) may be instructed to enter dormancy by bone marrow NG2+/Nestin+ mesenchymal stem cells." (PMID 36890838, 2023). "Studies have identified CD44+CD24− in breast cancer; CD44+CD24+EpCAM+ in pancreatic or ovarian cancer; and a high expression of neuron stem markers, such as CD133, CD44, and Nestin, and transcript factors, such as SOX2 and OCT4, in GBM." (PMID 34069945, 2021). "Pooled results demonstrated that positive expression of nestin predicted shorter BCSS and reduced OS of breast cancer patients in both univariate and multivariate analyses." (PMID 32467665, 2020).
breast carcinoma (continued). "Several established markers of breast cancer CSCs, including CD44+/CD24−/low phenotype and CD133, ALDH1, EpCAM, and nestin overexpression, have been correlated with poorer prognosis diagnosed patients." (PMID 33375383, 2020). "Breast cancer metastases (n = 164) from various anatomical sites were retrospectively analyzed by immunohistochemistry for FOXA1, Nestin and GATA3 expression." (PMID 30819139, 2019). "Immunohistochemical analysis of FOXA1 and Nestin expression in breast cancer metastases revealed FOXA1-positivity and Nestin-positivity in 52 and 16% of the metastatic samples, respectively." (PMID 30819139, 2019). "Nestin is known to be a neural stem cell marker, and is expressed in CSC, which play important roles in the progression and metastasis of breast cancer." (PMID 25056574, 2014). "Structural proteins reported to have increased expression in basal-like breast carcinomas include basal cytokeratins (CK5/6, CK14 and CK17), vimentin, fascin, nestin and moesin." (PMID 24281106, 2010). "In breast cancer, TGF-β2 and BMP7 derived from NG2+/Nestin+ MSCs maintains dormancy." (PMID 41091336, 2025). "As a number of studies in Atypical Theratoid/Rabdoid Tumor (AT/RT) and breast cancer have shown, DSF with the addition of Cu++ reduced the expression of cancer stem-like cells (CSCs) by decreasing levels of ALDH, CD133 and Nestin, three markers of CSCs in brain malignancies." (PMID 34731160, 2021). "Up to our knowledge so far, no study has evaluated serum Nestin in patients with different stages of breast cancer compared to healthy control women." (PMID 33584136, 2021). "Nestin is an independent prognostic factor for worse BCSS and OS of breast cancer patients." (PMID 32467665, 2020). "Triple-negative breast cancers have significantly higher NES (nestin) mRNA expression than the other breast carcinoma subtypes." (PMID 30819139, 2019). "We here examined whether Nestin, by protein and mRNA levels, could be a predictor of BRCA1 related breast cancer, a basal-like phenotype, and aggressive tumours." (PMID 28439082, 2017). "Expression of CK5 and nestin was used for the categorization of TNBC into basal (TN, CK5+, and/or nestin+) and non-basal (TN, CK5−, and/or nestin−) phenotypes, and Kaplan–Meier curves were used for estimation of overall survival and breast cancer-specific survival (BCSS)." (PMID 32850312, 2020). "Therefore, nestin is an independent factor for worse BCSS and OS of breast cancer patients." (PMID 32467665, 2020). "In addition, Nestin-positive breast carcinomas lacked CCND1 and TOPA2A gene amplification and occasionally harbored MYC gene amplification." (PMID 30819139, 2019).
pancreatic cancer (38 papers, 2012 to 2026). "Nestin is highly associated with angiogenesis, as it is expressed by newly formed blood vessels during embryogenesis and in various tumor tissues, including prostate and pancreatic cancers." (PMID 31126068, 2019). "Recent investigations have revealed that nestin is also a cancer stem-cell marker, and it contributes to pancreatic cancer development." (PMID 35625561, 2022). "BMI1, ALDH1A1, CXCR4, EpCAM, OCT-4, c-MYC, and NESTIN are cancer stemness-related markers of pancreatic cancer." (PMID 35806187, 2022). "Our data show that expression of αA-crystallin is significantly lower in majority of pancreatic cancer cell lines compared with the nestin-expressing normal pancreatic cancer cells (HPNE cells)." (PMID 27588467, 2016). "To address the expression of the putative CSC markers CD24, CD44, EpCAM, CD133, and nestin in pancreatic cancer, we used three cell lines (P6B, P28B, and P34B) derived from PDAC tumor tissues and three corresponding FFPE tumor samples." (PMID 27414409, 2016). "Some studies have reported that nestin expression in vascular sarcoma, pancreatic cancer, and gastrointestinal stromal tumors is closely correlated with the degree of malignancy and patient prognosis." (PMID 24966803, 2014). "Recent reports have shown that expression of nestin in breast, prostate, and pancreatic cancer is positively correlated with tumor malignancy." (PMID 24498263, 2014). "In chronic pancreatitis and pancreatic cancer, an up-regulation of nestin in intrapancreatic glial cells was observed indicating a potential de-differentiation of intrapancreatic glial cells." (PMID 24780093, 2014). "During later stages of pancreatic tumor, we also found a strong expression of specific genes related to stemness (e.g. cdh2 (N-Cadherin) and nestin), confirming the activation of EMT." (PMID 24878567, 2014). "Recently, Matsuda and colleagues illustrated the importance of Nestin in pancreatic cancer cell migration, invasion and metastasis by selectively modulating the expression of actin and other cell adhesion molecules." (PMID 24625091, 2014). "Subsequent reports have shown that nestin is expressed in breast, prostate and pancreatic cancer, and is positively correlated with tumor malignancy." (PMID 24966803, 2014). "To further evaluate miR-200c expression in pancreatic cancer cell lines, we assayed a panel of 8 pancreatic cancer cell lines, as well as a normal, immortalized nestin-expressing pancreatic cell line (HPNE)." (PMID 24143167, 2013). "Our data are in line with a recent report suggesting nestin as a novel target for metastatic pancreatic cancer." (PMID 24086245, 2013). "Knockdown of nestin with siRNA decreases migration and invasiveness of pancreatic cancer cell lines." (PMID 24160469, 2013). "Our group recently reported that expression levels of nestin directly correlate with migration, invasion and metastasis of pancreatic cancer cells." (PMID 22580387, 2012). "It is interesting to note that nucleolin and nestin are expressed both by tumor cells and angiogenic ECs in pancreatic tumors, suggesting that potential targeted therapies could act via different cell types of the TME." (PMID 34503252, 2021). "Nestin is essential for TGF-β1/Smad mediated EMT in pancreatic cancer." (PMID 33919917, 2021). "We started with pancreatic cancer CSCs (PANC-1 CSLC and PSN-1 CSLC) and determined the effect of dexamethasone on the expression of stem cell–associated markers (CD133, Sox2, Nanog, Bmi1, and Nestin) and the differentiation marker E-cadherin." (PMID 33115754, 2020). "Moreover, PCR analysis showed significantly increased expression of B3GNT5 mRNA in highly metastatic FG, T3M-4 and HPAF pancreatic cancer cell lines compared to HPNE (hTERT-immortalized human pancreatic epithelial nestin-expressing) cell line." (PMID 31273306, 2019).